PRLR (prolactin receptor)
Diseases named in the same sentence as PRLR in open-access papers (continued):
Sharing a sentence is not in itself a finding about the gene and the disease.
glioma (4 papers, 2013 to 2023). A benign or malignant brain and spinal cord tumor that arises from glial cells (astrocytes, oligodendrocytes, ependymal cells). "Inflammatory microglial cells, dendritic cells, myeloid cells, and glioma stem cells were highly expressed in GBM tissue, and ACP7, EPPK1, PCDHA8, RHOD, DRC1, ZIC3, and PRLR were significantly associated with survival." (PMID 36836422, 2023). "Our study proposes PRLR as a therapeutic target for the treatment of GBM and warrants further evaluation of PRL and PRLR as prognostic biomarkers in glioma patients." (PMID 31862900, 2019). "Meta-analysis of transcriptomic data indicated that PRLR was expressed in all grade II-III glioma (GII-III) and GBM samples." (PMID 31862900, 2019). "In terms of GBM, a large-scale transcript profiling experiment detected PrlR mRNA in different glioma cell lines." (PMID 27788487, 2016). "PrlR was examined by immunofluorescence (IF) microscopy in cultured U251-MG, U87-MG and U373 glioma cells and IF signals were detected in the cytoplasm of these cells." (PMID 27788487, 2016). "PRLR expression has been found in rat and human glioma cells but also in benign intracranial tumors." (PMID 24257371, 2013). "To investigate the potential role of PRLR in glioma tumor cells, we examined the expression levels and functionality of endogenous PRLR in two glioma cell lines (G28 and G55)." (PMID 24257371, 2013). "Moreover, further development of lower grade glioma models is required to clarify why the activation of PRL/PRLR signalling elicit opposite outcomes between GII-III and GBM patients." (PMID 31862900, 2019). "We next aimed to evaluate the expression of PRL and PRLR in human glioma samples." (PMID 31862900, 2019). "It is therefore tempting to speculate that the combined application of ES and Tum triggers up-regulation of PRLR in glioma, resulting in augmented PRL signalling and ultimately in increased tumor growth and/or stimulation of angiogenesis." (PMID 24257371, 2013). "Our in vitro data confirm to some extent this hypothesis as they show for the first time that PRLR overexpression significantly increases glioma cell growth." (PMID 24257371, 2013). "Interestingly, we observed a strong up-regulation of PRLR in glioma cells treated with ES + Tum in vitro." (PMID 24257371, 2013). "Finally, we found an up-regulation of the prolactin receptor in tumor cells treated with the ES + Tum combination and demonstrate a role of this receptor in the control of glioma cell proliferation in vitro." (PMID 24257371, 2013). "ES + Tum-induced up-regulation of PRLR in glioma cells was also found in in vitro." (PMID 24257371, 2013). "Summarizing, PRL/PRLR signalling may elicit very different outcomes depending on the biological sex of the patient and glioma grade, factors that need to be taken into consideration before translating therapies using PRLR antagonists to the neuro-oncology clinic." (PMID 31862900, 2019). "However, only little is known about the role of the PRLR/PRL-signaling axis in glioma cells." (PMID 24257371, 2013). "When we examined the survival of glioma patients according to the local expression of PRL or PRLR we found no significant changes, neither in the overall survival of PRL+ vs. PRL− GII-III or GBM patients, nor in the overall survival of PRLRHIGH vs. PRLRLOW." (PMID 31862900, 2019). "Moreover, we found a 4fold up-regulation of PRL expression in PRLR-overexpressing cells when compared to mock-transfected cells, suggesting a PRL-autocrine loop that stimulates glioma cell growth." (PMID 24257371, 2013). "Similar results were obtained in vitro after immunofluorescence staining for cleaved caspase-3 and PRLR in glioma cells treated with ES + Tum (data not shown)." (PMID 24257371, 2013).
Hyperglycemia (4 papers, 2013 to 2024). An increased concentration of glucose in the blood. "Ten-week-old WT and PRLR−/− mice injected with leptin antagonist presented fasted hyperglycemia compared to control saline injected mice." (PMID 24667351, 2014). "However, the effects of sulpiride reducing hyperglycemia were also observed in obese prolactin receptor null mice." (PMID 38635745, 2024). "Several carbohydrate metabolism genes involved in metabolism of monosaccharide and carbohydrate and hyperglycemia (e.g. CPT1A, GALK1, INS, LEPR, PRLR and SCD) are highly expressed in mouse CPE and only lowly in human CPE." (PMID 24391755, 2013).
melanoma (4 papers, 2016 to 2021). A malignant, usually aggressive tumor composed of atypical, neoplastic melanocytes. "Since prolactin is also secreted by the anterior pituitary hormone and serves autocrine functions and prolactin receptor is expressed in melanoma cells, we also examined the effect of prolactin on melanoma growth in vivo." (PMID 27825319, 2016). "In view of these facts and our identification of a profound GH mediated regulation of melanoma progression, we wanted to look at presence of endogenous RNA levels of GH as well as PRL and PRLR in human melanoma." (PMID 28223541, 2017). "Although we observed a mild increase in either PRL or PRLR in the human melanoma cell lines due to doxorubicin, we did not observe any upregulation of MITF or MITF targets due to PRL addition." (PMID 31547367, 2019). "Like our studies, PRLR-inhibited/down regulated models can provide a mechanistic detail of PRL action and a putative salvage pathway involving GH-PRLR interaction specifically in melanoma." (PMID 28223541, 2017).
meningioma (4 papers, 2013 to 2021). A generally slow growing tumor attached to the dura mater. "These modest findings are also surprising in light of the previously reported prolactin receptor expression in up to 40–60% of meningiomas." (PMID 34359779, 2021). "This study sets out to investigate prolactin and prolactin receptor status in 29 patients with pregnancy-related meningiomas in Denmark, from January 1972 to December 2016, as compared to 68 controls aged 20–45 years, also undergoing resection of a meningioma." (PMID 34359779, 2021). "Combined with the findings that 40–60% of meningiomas are prolactin receptor-positive, the authors raise the hypothesis that meningioma growth during pregnancy may be affected by prolactin." (PMID 34359779, 2021). "In this case–control study including the majority of patients with pregnancy-related meningiomas in Denmark 1972–2016, we investigated the presence of prolactin and the prolactin receptor status in the resected meningiomas, compared to meningiomas from female controls within the same age group." (PMID 34359779, 2021). "Interestingly, some increase in prolactin receptor levels in meningiomas has been also reported earlier." (PMID 31649887, 2019). "Studies investigating prolactin receptor status in meningiomas resected from pregnant or lactating women could not be found in the literature, possibly due to the extremely rare occurrence." (PMID 34359779, 2021).
migraine (4 papers, 2021 to 2025). "Downregulation of the protective long prolactin receptor isoform further increases susceptibility to migraine‐relevant triggers." (PMID 41052788, 2025). "Second, a new line of evidence has shown that prolactin receptor expression and neuronal responsiveness to external stimuli and stress are different in female and male laboratory animals, which can explain some mechanisms underlying sex-related differences in migraine, with a spotlight on prolactin." (PMID 34737888, 2021). "Clinical and preclinical studies have postulated a role for PRL and PRLR in headache disorders, particularly migraine." (PMID 36967387, 2023). "Regarding the relationship between PRL signalling and migraine (or prolactinoma- and/or pituitary diseases-associated headaches), clinical and preclinical studies have suggested the involvement of PRL and PRLR in headache disorders." (PMID 36967387, 2023). "Following this rationale, treatments targeting PRL nociception should specifically target the PRLR in certain migraine pain-related structures, such as the cranial trigeminal system." (PMID 36967387, 2023). "In animal studies, PRL administered to the dura mater elicited migraine-like behaviour only in females, and PRLR was more abundant in the female sex in trigeminal neurons." (PMID 36967387, 2023). "In terms of the inflammatory side of migraine, PRLR is known to be expressed on CGRP-immunopositive sensory fibres and promotes the release of CGRP." (PMID 36967387, 2023). "Therefore, migraine treatment targeting prolactin should aim to block its effects using prolactin receptor antagonists or monoclonal antibodies specifically acting at migraine-pain related structures." (PMID 36967387, 2023). "An increasing number of studies have shown that the expression of a prolactin receptor in female nociceptors and their responses to external stimuli such as stress are different, which can help explain the female sex-dominant feature of migraine." (PMID 34737888, 2021). "Moreover, prolactin receptor antagonism attenuated dural CGRP-induced migraine-like behaviours." (PMID 40168298, 2025). "Based on these results, they reported that PRL levels and PRLR signals are increased in females in a mouse model for medication overuse headache, suggesting a potential role of the hypothalamus and the neuroendocrine system in the chronicity of migraine, especially in females." (PMID 36967387, 2023). "Considering that PRL and PRLR display a sex-dependent activity, PRL signalling might represent an important approach in understanding sexual dimorphism in the pathophysiology of pain and migraine." (PMID 36967387, 2023). "Besides the direct link between PRL and (migraine) pain, the relationship between inflammation and PRL raises the question whether blocking PRLR can be used in migraine pain—not only as a preventive but also as a treatment that targets pathophysiological mechanisms of migraine." (PMID 36967387, 2023).
pituitary adenoma (4 papers, 2018 to 2023). "Due to the limitations of the clinical data, in vitro experimentation was conducted to determine the potential effects of estrogen or PRL on their canonical pathways, including ERα, pERα, PRLR and D2R expression in pituitary adenoma cells." (PMID 33173437, 2020). "ERα inhibition abolished E2-induced PRLR upregulation and PRL-induced ERα phosphorylation, and fulvestrant, an ERα inhibitor, restored pituitary adenoma cell sensitivity to bromocriptine by activating JNK-MEK/ERK-p38 MAPK signaling and cyclin D1 downregulation." (PMID 33173437, 2020).
atherosclerosis (3 papers, 2011 to 2023). A disease characterized by the build-up of fatty material and calcium deposition in the arterial wall resulting in partial or complete occlusion of the arterial lumen. "The demonstration of the intense prolactin receptor expression on advanced human coronary atherosclerotic plaques supports the role of prolactin on the development of atherosclerosis." (PMID 21331754, 2011).
Fibroadenoma (3 papers, 2019 to 2023). A benign tumor of the breast characterized by the presence of stromal and epithelial elements. "Mutated PRLRs can be detected in fibroadenomas, and the mutation in the PRLR is associated with increased serum PRL levels." (PMID 36845388, 2023). "Surprisingly, we observed that stromal cells in fibroadenoma barely expressed hormone receptors (ER, PR, PRLR), while the epithelium expressed high levels of hormone receptors." (PMID 37328469, 2023).
Gynecomastia (3 papers, 2012 to 2016). Abnormal development of large mammary glands in males resulting in breast enlargement. "In a series of 30 patients with male gynecomastia and 30 patients with MBC, prolactin receptor expression was significantly higher in the MBC patients than in the patients with gynecomastia." (PMID 27655704, 2016). "Compared to gynecomastia, prolactin receptor expression was remarkably higher in MBC." (PMID 26612408, 2015).
invasive breast carcinoma (3 papers, 2007 to 2025). A carcinoma that infiltrates the breast parenchyma. "We found that PRLR expression to be significantly downregulated in invasive breast cancer, only 21% of invasive cases showed detectable expression of the PRLR in comparison with normal/benign (80%) and in situ carcinoma (60%)." (PMID 36157462, 2022).
invasive carcinoma (3 papers, 2008 to 2019). A carcinoma that is not confined to the epithelium, and has spread to the surrounding stroma. "For this study, specimens previously shown to have ADH, DCIS, or invasive carcinoma only minimally expressing STAT5a (mean immunoscores 1.0–1.2) were examined for PRLR." (PMID 21655368, 2008). "Importantly, the extent of co-expression of these receptors in invasive carcinomas significantly declined to only 29.5% for PRLR/TGFβR1 (p = 0.02) and 28.12% for PRLR/TGFβR2 (p = 0.049)." (PMID 30987013, 2019). "Reversal of the expression seen in normal cells in DCIS and invasive carcinoma, resulting in increased PRLR and decreased STAT5a, may indicate a signaling pathway disturbance and possibly a divergence related to carcinogenesis." (PMID 21655368, 2008). "Using a cross with SV-40T oncogene transgenics and prolactin receptor null mice, and transplant of the epithelium to endocrine normal mice, the prolactin receptor was demonstrated to increase neoplasia and positively impact the transition to invasive carcinoma." (PMID 19014541, 2008).
invasive ductal carcinoma (3 papers, 2008 to 2019). "Indeed, the co-expression between PRLR and both TGFβ receptors was found to be reduced by around 50% in invasive ductal carcinoma cases that are characterized by LN involvement compared with cases with no LN involvement (from ~30% to 15%)." (PMID 30987013, 2019). "Transcripts significantly overexpressed in ductal adenocarcinomas include CD24, CDH23 (cadherin-like 23), and PRLR (prolactin receptor)." (PMID 29581876, 2018). "Combined with the over-expression of PRLR, lack of detectable STAT5a in the nuclei of in situ and invasive ductal carcinoma suggests the possibility of attempted STAT5a activation that has been inhibited." (PMID 21655368, 2008).
prolactinoma (3 papers, 2022). "Nevertheless, in 2019, two germline PRLR intracellular domain variants were later associated with prolactinoma manifestation." (PMID 36714572, 2022).
schizophrenia (3 papers, 2021 to 2022). A major psychotic disorder characterized by abnormalities in the perception or expression of reality. "In our own studies, we identified that Penfluridol, which has been approved for the treatment of schizophrenia, binds to PRLR at the JAK2 binding site within the intracellular domain." (PMID 36714582, 2022). "Other candidate genes, PRL-releasing hormone receptor (PRLRH), PRL receptor (PRLR), oxytocin (OXT), oxytocin receptor (OXTR), and NPY, may also correlate with the PRL pathway and contribute to schizophrenia and T2DM." (PMID 33315097, 2021). "However, genetic data on PRLRH, PRLR, OXT, OXTR, and NPY in human T2DM and schizophrenia patients are scarce." (PMID 33315097, 2021).
alopecia areata (2 papers, 2019 to 2024). Loss of scalp and body hair involving microscopically inflammatory patchy areas. "Not only was the expression of the PRLR significantly increased in patients with alopecia areata, but its expression correlated with disease severity." (PMID 39000207, 2024). "Whether PRL and PRLR signalling play a significant role in the aetiopathogenesis of alopecia areata, potentially related to psychological stress, and to what extent this is due to systemic versus intracutaneous PRL production remain to be clarified." (PMID 39000207, 2024).
cardiac hypertrophy (2 papers, 2022 to 2024). "In addition, prolactin receptor expression appears to be linked to myocardial hypertrophy." (PMID 38672089, 2024). "And PRLR protein expression was increased in hypertrophy hearts, and involved in the development of cardiac hypertrophy." (PMID 36402964, 2022).
colorectal cancer (2 papers, 2011 to 2026). A primary or metastatic malignant neoplasm that affects the colon or rectum. "To date, several lines of evidence suggest the involvement of the hPRL/PRLR axis in breast, prostate and colorectal cancer development." (PMID 21505459, 2011). "The COLO320 line was chosen as it is also one of the few available colorectal cancer cell lines via ATCC that is derived from a female patient and positive for the prolactin receptor, allowing us to explore the phosphorylation of STAT3 in response to prolactin treatment." (PMID 41501898, 2026).
depression (2 papers, 2022 to 2024). "Prolactin receptor (PRLR), an antidepressant factor, participates in depression by the JAK2–STAT5 signaling pathway." (PMID 36844911, 2022).
Ductal carcinomas (2 papers, 2010 to 2016). "Among the histological subtypes the lowest gene expression levels of ESR1, PGR and PRLR were found in solid, anaplastic and ductal carcinomas." (PMID 27649560, 2016). "Furthermore, the gene expression of ESR1, PGR and PRLR were significantly lower in solid, anaplastic and ductal carcinomas compared to the reference tissue." (PMID 27649560, 2016). "Ductal carcinomas showed low ESR1/PGR and PRLR gene expression as well, even though it has been shown that they have a low tendency to invade lymphatic vessel." (PMID 27649560, 2016). "Among the histological subtypes, solid carcinoma (p = 0.004), anaplastic carcinoma (p = 0.009), ductal carcinoma (p = 0.018) and carcinoma arising in a benign tumor (p = 0.049) exhibited significantly lower PRLR expression levels than non-neoplastic mammary tissue of fresh frozen samples." (PMID 27649560, 2016).
endometrial carcinoma (2 papers, 2016 to 2021). A malignant tumor arising from the epithelium that lines the cavity of the uterine body. "This work aims to review the most important findings regarding the PRL/PRLR axis in cervical, ovarian, and endometrial cancers and its molecular mechanisms to support carcinogenesis." (PMID 34745013, 2021). "In addition to this, it has been found that the PRLR is overexpressed in breast, cervical, ovarian, and endometrial cancer (EC) in comparison with their respective cancer-free tissues." (PMID 34745013, 2021).
endothelial dysfunction (2 papers, 2024). In vascular diseases, endothelial dysfunction is a systemic pathological state of the endothelium (the inner lining of blood vessels) and can be broadly defined as an imbalance between vasodilating and vasoconstricting substances produced by (or acting on) the endothelium. "Additionally, the serum level of prolactin and prolactin receptor, supposedly associated with endothelial dysfunction, pathological remodeling, and compromised cardiovascular health, was significantly reduced by ARNI and slightly by captopril." (PMID 38672089, 2024). "Levels of PRL, and by extension, lactogenic signaling via the PRLR, are not consistently associated with the risk of cardiovascular events, even though excess prolactin elevates the risk of endothelial dysfunction and metabolic disorders." (PMID 39796124, 2024).
HCMV infection (2 papers, 2020). "Next, we examined the effects of HCMV infection on PRLR transcript levels in SKOV3 cells at 1, 3, and 5 dpi." (PMID 32121009, 2020). "The prolactin receptor (PRLR) and human cytomegalovirus (HCMV) proteins are frequently detected in ovarian tumor tissue specimens, but the potential impact of HCMV infection on the PRL system have so far not been investigated." (PMID 32121009, 2020).
Hypertension (2 papers, 2013 to 2024). The presence of chronic increased pressure in the systemic arterial system. "Among the highly down-regulated genes in the MCA of the hypertension group were SST, ADAM6, and PRLR." (PMID 23874591, 2013).